MVP (major vault protein)
Diseases named in the same sentence as MVP in open-access papers (continued):
Sharing a sentence is not in itself a finding about the gene and the disease.
cancer (76 papers, 1997 to 2025). A tumor composed of atypical neoplastic, often pleomorphic cells that invade other tissues. "Components of the vault protein have additionally been implicated in certain cancers, including colorectal cancer, with MVP implicated in the migration of cancer cells and facilitation of metastasis." (PMID 41373720, 2025). "Our findings unveiled a significant association between MVP expression and cancer progression, with higher expression levels predicting poorer overall survival in multiple cancer types." (PMID 38713157, 2024). "After treatment with FUS‐induced hyperthermia effect, several markers associated with cancer progression and drug resistance were down‐regulated, such as major vault protein (MVP), calumenin (CALU), and heat shock 70 kDa protein 5 (HSPA5)." (PMID 38041509, 2024). "MVP or vaults have previously been found to be overexpressed in multidrug-resistant cancer cells and implicated in various cellular processes such as cell signaling and innate immunity." (PMID 38956386, 2024). "MVP, the major vault protein, was shown to be linked to multidrug resistance in a series of cancers including PCa, and was recently proposed as a biomarker for lethal outcomes in PCa by Ramberg and colleagues." (PMID 35159020, 2022). "The most abundant protein recovered was the major vault protein (MVP), implicated in various drug resistance mechanisms in cancer cells." (PMID 31848338, 2019). "In addition, adipose tissue has been shown to increase the expression of major vault protein (MVP) in cancer cells, causing resistance to doxorubicin, an anthracycline." (PMID 37184128, 2023). "Thus, it can be concluded that MVP misregulation is clearly implicated in tumorigenesis, but the exact role of MVP during tumorigenesis varies depending on the cancer type." (PMID 35681764, 2022). "MVP, a known lung resistance protein, is a major component of a ribonucleoprotein organelle called vault, and which has been implicated in multiple drug resistance of cancer cells." (PMID 30131696, 2018). "Furthermore, the expression of MVP was associated to a malignant phenotype in some cancers, indicating a direct involvement in tumour development and progression." (PMID 22931894, 2012). "Altogether, single-cell signaling analyses with our Ras-LOCKR tools enabled the discovery of MVP’s role in facilitating the resistance of a subpopulation of cancer cells to KRas-G12C inhibitors." (PMID 39103633, 2025). "The Major vault protein (MVP) serves to regulate chemosensitivity in cancer metabolism, a recurrent challenge encountered during cancer treatment." (PMID 40100070, 2025). "Increasing evidence has demonstrated that MVP plays a critical oncogenic role in multiple cancer types." (PMID 40586636, 2025). "This expanded body of research underscores the complexity of MVP’s involvement in cancer progression." (PMID 40004027, 2025). "These pathways play critical roles in regulating cell survival, proliferation, and apoptosis, further highlighting MVP’s pivotal role in cancer development and progression." (PMID 40004027, 2025). "A recent analysis across 38 different cancer types highlighted MVP’s critical role in shaping the tumor immune landscape." (PMID 40004027, 2025). "As several cancer therapies are associated with increased MVP expression, our results reaffirm the role of MVP in drug resistance and we wonder whether these MVP-mediated mechanisms may be generally involved in resistance to new inhibitors against other Ras mutants and perhaps other cancer drugs." (PMID 39103633, 2025). "It has been confirmed that MVP expression is related to occurrence of drug resistance in cancer cells." (PMID 40586636, 2025). "The landscape of genetic alterations of MVP in pan-cancer were detected via the cBioPortal database, which unveiling a prevalence pattern of genetic variation in MVP within the cancer spectrum." (PMID 39026679, 2024).
cancer (continued). "This pan-cancer study aimed to investigate expression of MVP and its correlation with clinical outcomes and immune infiltration across diverse cancer types." (PMID 38713157, 2024). "Extensive investigations have been conducted to explore the role of MVP in specific cancer contexts, yet the potential molecular mechanisms and biological functions of MVP in PAAD still remain considerably elusive." (PMID 39026679, 2024). "The role of TEP1, MVP, and vPARP is reported in various cellular processes and diseases, such as multidrug resistance, apoptosis, cancer progression, and epilepsy." (PMID 38612882, 2024). "The mean levels of MVP in sera were elevated in all cases of inflammation (infection, cancer, other type) as compared to healthy individuals (t = 8.4, p < 0.0001; t = 6.0, p < 0.0001; t = 7.6, p < 0.0001)." (PMID 39338437, 2024). "These compelling results suggest that MVP holds promise as a valuable biomarker for prognostic assessment and the development of immunotherapeutic strategies across various cancer types." (PMID 38713157, 2024). "To explore the role of MVP in immune infiltration of M2-like TAMs in other cancers, we examined the MVP expression level and the immune infiltration level of M2-macrophages in The Cancer Genome Atlas (TCGA) tumors from TIMER2.0." (PMID 38264642, 2023). "As expected, the expression level of MVP was positively correlated with the infiltration level of M2 macrophages in most types of cancers." (PMID 38264642, 2023). "Three proteins have not previously been associated with FTC, but are related to thyroid function or other types of cancer, namely, major vault protein (MVP), GEM‐interacting protein (GMIP) and galectin‐9 (LGALS9)." (PMID 35194950, 2022). "Through this binding, MVP and the vault complex can mediate diverse intracellular responses in various cell types including cancer cells." (PMID 35681764, 2022). "MVP is also closely connected to signaling pathways in cancer cells, and upregulation most often results in chemotherapy resistance of the cells." (PMID 35681764, 2022). "We assessed the expression of ABC-transporters, MVP, YB-1, and analyzed their correlation with chemosensitivity of cancer cells." (PMID 35328603, 2022). "Among all the signaling pathways that have been shown to have a connection to the MVP or the vault complex, proliferation and apoptosis are particularly important with respect to cancer." (PMID 35681764, 2022). "MVP is overexpressed in multidrug-resistant cancer cells, however, whose functions are poorly understood." (PMID 35246039, 2022). "Together, this supports MVP as a critical factor in the cancer genesis, proliferation and propagation over the organism." (PMID 34829999, 2021). "In fact, total inhibition of MVP expression in certain cancer cell types (HAP1) resulted in the death of the cells’ population." (PMID 34829999, 2021). "Major vault protein (MVP) is the main structural protein of the vault complex that has already been investigated in specific cancers." (PMID 35433709, 2021). "MVP-mediated miRNA193a extrusion resulted in active cancer cell proliferation, whereas MVP knockout was paralleled by intracellular miR193a buildup with ensuing inhibition of tumor progression." (PMID 33572350, 2021). "Previous studies demonstrated a discrepancy in the role of MVP in the development of resistance in cancer cells." (PMID 34829999, 2021). "This work is the first comprehensive research to determine the expression level, relationship with clinical parameters, pathological characteristics, molecular hallmarks, TIICs, and cancer-immunity cycle functions of MVP in PTC." (PMID 35433709, 2021). "Intriguingly, MVP expression was positively correlated with multiple distinct phases of the anti-cancer immunity cycle." (PMID 35433709, 2021). "Functionally, enrichment analysis provided new clues for the close relationship between MVP with cancer-related signaling pathways and the immune microenvironment in PTC." (PMID 35433709, 2021).
cancer (continued). "Taken together, high MVP expression was connected with anti-cancer immune activity and was instrumental in the regulation of the cancer-immunity cycle." (PMID 35433709, 2021). "In another study, the immunobistocbemical expression of MVP protein in freshly frozen normal human tissues and in 174 cancer specimens of 28 tumor types was analyzed, showing a broad distribution of MVP in both normal and tumoral human tissues." (PMID 31261673, 2019). "One interesting finding in our study was that MVP expression was higher at the invasive front of human tumors, where cancer cells are at close proximity with adipocytes, than in the tumor center." (PMID 31143368, 2019). "By examining 120 patients with NSCLC, we found that MVP expression was significantly up-regulated in cancer tissues compared with the paired normal tissues." (PMID 31092229, 2019). "Although MVP is overexpressed in the drug-resistant cancer cells, the definite role of it in NSCLC is still a disputable issue." (PMID 31092229, 2019). "Despite some controversy, overexpression of MVP has been correlated with the degree of malignancy and drug resistance, resulting in a poor prognosis for cancer treatment with several drugs, including DOX." (PMID 30654824, 2019). "MVP expression was analyzed either in the tumor center or at the tumor border, where cancer cells are in close contact with adipocytes, the areas of interest being first selected on HE slides by the pathologist." (PMID 30654824, 2019). "MVP is being considered as a drug resistant biomarker in NSCLC: because this is being up-regulated in many cancer cell lines, i.e., A549, Calu-3 and Calu-6." (PMID 30131696, 2018). "Major vault protein induces cancer cell drug resistance not only due to intracellular distribution of DDP, but also contributes to regulation on mTORC2/AKT axis." (PMID 30131696, 2018). "To figure out how MVP translocates to the cell surface, we treated Huh7 cells with some chemical inhibitors of cancer cell signaling pathways." (PMID 29038587, 2017). "Although MVP is distributed in diverse normal tissues, its expression is upregulated in multidrug-resistant cancer cells." (PMID 29038587, 2017). "The findings that MVP and vaults are upregulated in multidrug-resistant cancer cells supported the concept that vaults play a role in drug resistance." (PMID 27275002, 2016). "Multiple in vitro studies demonstrated that MVP is almost generally overexpressed in drug-resistant human cancer cells selected against diverse chemotherapeutic agents." (PMID 24243798, 2013). "The estimated effects of MVP overexpression appeared somewhat larger in the tongue cancer patients compared with the tonsil cancer patients for loco-regional failure and cancer-specific death." (PMID 22931894, 2012). "Multiple preclinical studies have corroborated this link between MDR and the MVP expression level in cancer cells, despite some contradicting studies and the fact that the MVP knockout mouse does not show enhanced hypersensitivity to cytostatics." (PMID 22040803, 2011). "MVP has been detected in 78% of 61 human cancer cell lines, and its expression levels correlate with resistance against a variety of MDR-related and unrelated drugs." (PMID 22040803, 2011). "Many investigations highlight MVP’s significant role in influencing the immune response in cancer." (PMID 40004027, 2025). "By relating signaling complex composition with Ras-LOCKR-PL and localized Ras activities with Ras-LOCKR-S at the single-cell level, we identified MVP as being necessary for the adaptations that a subpopulation of cancer cells adopt in response to Ras-G12C–GDP inhibition." (PMID 39103633, 2025). "Thus, the MVP ribonucleoprotein complex was shown to inhibit cancer cell proliferation and survival via the inhibition of STAT3 signaling and enhancement of HIF1α." (PMID 40243914, 2025).
cancer (continued). "These discoveries illuminate that MVP has made diverse and meaningful contributions to oncology research, underscoring its crucial role in the intricate network of molecular events that govern cancer progression." (PMID 39026679, 2024). "Moreover, MVP (also known as LRP, lung resistance-related protein) is generally overexpressed in human cancer cells and is involved in resistance phenotype formation." (PMID 38612882, 2024). "We further validated expression of MVP and function in cancer cell lines A549 and AGS." (PMID 38713157, 2024). "Subsequent research has further elucidated the multiple roles of MVP in cancer biology." (PMID 39026679, 2024). "Moreover, since many studies did not separate the contribution of free vtRNA from vtRNA bound to the vault RNP, we additionally summarized the contribution of the vault complex and the MVP to cancer, including drug resistance, proliferation and apoptosis." (PMID 35681764, 2022). "By quantifying the immune infiltrating cellular component using three different algorithms (quanTIseq, MCPcounter, and CIBERSORT), we found that PTCs with high MVP expression were dramatically correlated with the high infiltrating level of anti-cancer CD8+ T cells and pro-cancer regulatory T cells." (PMID 35433709, 2021). "Recently, the literature has shown that MVP played an important part in cancer progression." (PMID 35433709, 2021). "Based on the large body of research presented above, MVP upregulation has also been identified as a prognostic biomarker for radio- and chemotherapy resistance and as having poor clinical outcomes in plenty of cancer diseases." (PMID 33572350, 2021). "A recent report also suggests that forced MVP expression may be sufficient per se to induce cancer development." (PMID 33572350, 2021). "The MVP-interacting domain binds MVP, which responds to xenobiotic exposure and serves as a scaffolding protein in signaling and intracellular transport pathways, increasing malignancy in certain types of cancer, including colon cancer." (PMID 32316696, 2020). "Major vault protein (MVP) is the major component of vault, a eukaryotic organelle involved in multiple cellular processes, and is important in multiple cellular processes and diseases including the drug resistance in cancer chemotherapies." (PMID 31092229, 2019). "This could lead to a loss of information especially when investigating the impact of obesity, since we consistently show that the cancer cells/adipocytes cross-talk occurs at the tumor invasive front including MVP overexpression, a drug resistance protein." (PMID 31143368, 2019). "Here, we hypothesized that the anti-cancer effect of YPFS+GF could be partly accounted by regulation of MVP." (PMID 30131696, 2018). "Due to the overexpression of MVP in several P-glycoprotein-negative chemoresistant cancer cell lines (P-gp/neg), vaults have been linked to multidrug resistance (MDR)." (PMID 28623509, 2017). "In addition, the expression of MVP correlated with the degree of malignancy in certain cancer types, suggesting a direct involvement in tumor development and/or progression." (PMID 28623509, 2017). "To figure out how MVP translocates to the cell surface, we treated Huh7 cells with some chemical inhibitors of cancer cell signaling pathways, and found that U0126 (ERK inhibitor) and rapamycin (mTOR inhibitor) obviously decreased cell surface expression of MVP." (PMID 29038587, 2017). "Major vault protein (MVP), also known as lung resistance protein, is a major component of a ribonucleoprotein organelle called vault, which has been implicated in drug resistance in cancer cells." (PMID 27558312, 2016). "Consequently, targeting MVP may offer a compelling therapeutic approach in the treatment of human cancers." (PMID 38713157, 2024). "Moreover, higher MVP expression is found at the invasive front in cancer cells closer to adipocytes, suggesting that MVP-mediated drug resistance may be clinically relevant." (PMID 36624542, 2023).
cancer (continued). "In summary, our findings elucidate that MVP may affect and regulate the cancer-immunity cycle." (PMID 35433709, 2021). "These early findings were subsequently confirmed by plenty of data reporting MVP upregulation and drug resistance evoked by drug exposure in several cancer cell types and tissues, although MVP upregulation may be observed in cancer even prior to drug treatment." (PMID 33572350, 2021). "Therefore, the MVP protein level in cancer patients could be explored as a predictive biomarker for identifying patients who may benefit from the combination of ECyd and platinum in future clinical trials." (PMID 25087851, 2014). "Consistent with this hypothesis, MVP has been found to be overexpressed in various multidrug-resistant cancer cell lines, together with a range of clinical samples such as H&N, ovarian, lung carcinomas, hepatoblastoma, acute myeloid leukemia, and multiple myeloma." (PMID 25087851, 2014). "In our study, we observed significantly elevated MVP expression in both TSCC tissues and cell lines compared to normal controls, which aligns with the oncogenic profile of MVP in other cancers." (PMID 40586636, 2025). "Major Vault Protein (MVP) is the principal structural component of the vault complex, and its expression level is remarkably upregulated in various cancers." (PMID 39026679, 2024). "Major Vault Protein (MVP) has emerged as a potential prognostic and immunological biomarker in various cancer types." (PMID 38713157, 2024). "Additionally, the expression of MVP may serve as a prognostic marker for several types of cancer." (PMID 37486921, 2023). "As it is well-known that drug transporters play a crucial role in cancer drug resistance, we examined the expression levels of several drug transporters, including ABCB1 (MDR1), ABCC1 (MRP1), ABCG2/BCRP, and LRP/MVP, in MDA-MB-231Tx cells by RT-PCR." (PMID 34944868, 2021). "Previous studies indicated the role of cellular vault proteins (MVP, TEP1, vPARP) in the resistance of cancer cells to various anticancer drugs." (PMID 34829999, 2021). "Major Vault Protein (MVP) is a main player in MDR, becoming upregulated in several cancer cell lines." (PMID 33322132, 2020). "MVP is also involving in several intracellular signal cascades, e.g., mTOR/AKT, EGFR/PI3K, as a result to promote drug resistance in cancer cells." (PMID 30131696, 2018). "Cell surface-expressed MVP (csMVP) was also detected on the surface of various HCC cell lines (Huh7, HepG2, and SNU-387), transformed hepatocytes (THLE-2), and some cancer cell lines (A549, H358, and Colo205) with α-MVP." (PMID 29038587, 2017). "Major vault protein (MVP), which is the main component of the vault complex, is over-expressed in many multidrug-resistant cancer cell lines, suggesting a possible role for MVP in cell signaling and survival." (PMID 23443088, 2012). "A number of cancer-related genes are located in these two RARs: NUPR1, MVP, MAPK3, FUS, and PYCARD are located in RAR-G12 while ERBB2, GRB7, and PPP1R1B are located in RAR-G13." (PMID 22938721, 2012). "The developed system encapsulated three different agents: adriamycin, as a cancer chemotherapeutic, as well as MVP-siRNA and BCL2-siRNA to inhibit the major vault protein (MVP) and the B-cell lymphoma-2 (BCL2) gene which are responsible for the multidrug resistance exhibited by the specific cells." (PMID 39065565, 2024). "Thus, we analyzed the expression of MVP across 15 diverse human cancers from the TCGA database through GEPIA2, and found that the expression of MVP was significantly increased in PAAD compared to normal tissues." (PMID 39026679, 2024). "The results suggest that MVP expression differed between the tumor and adjacent nontumorous tissues in most human cancers." (PMID 38264642, 2023). "Inhibition of MVP can result in the accumulation of miR-193a in the cell rather than in the exosomes, thereby suppressing cancer development." (PMID 35563246, 2022).